TLN1 (talin 1)
Description:
High molecular weight cytoskeletal protein concentrated at regions of cell-matrix and cell-cell contacts. Involved in connections of major cytoskeletal structures to the plasma membrane. With KANK1 co-organize the assembly of cortical microtubule stabilizing complexes (CMSCs) positioned to control microtubule-actin crosstalk at focal adhesions (FAs) rims.
Synonyms: TLN; ILWEQ; talin-1
Tractability: Antibody: its Gene Ontology location is reachable by antibodies, with high confidence; UniProt places it where antibodies can reach, with medium confidence; the Human Protein Atlas places it where antibodies can reach. PROTAC: ubiquitination databases record sites on it; its protein half-life has been measured.
Target class: Structural protein
Gene: Protein-coding gene on chromosome 9 (35,696,948 to 35,732,195, reverse strand). Ensembl gene ENSG00000137076.
Subcellular location: Cell projection, ruffle membrane; Cytoplasm, cytoskeleton; Cell surface; Cell junction, focal adhesion
Subcellular location (Human Protein Atlas): Cytosol; Focal adhesion sites; Centriolar satellite; Plasma membrane
Pathways (Reactome):
Disease: Paradoxical activation of RAF signaling by kinase inactive BRAF; Signaling by BRAF and RAF1 fusions; Signaling by RAF1 mutants; Signaling by high-kinase activity BRAF mutants; Signaling by moderate kinase activity BRAF mutants; Signaling downstream of RAS mutants
Signal Transduction: GRB2:SOS provides linkage to MAPK signaling for Integrins; Integrin signaling; MAP2K and MAPK activation; p130Cas linkage to MAPK signaling for integrins
Cellular responses to stimuli: High laminar flow shear stress activates signaling by PIEZO1 and PECAM1:CDH5:KDR in endothelial cells; XBP1(S) activates chaperone genes
Developmental Biology: SEMA3A-Plexin repulsion signaling by inhibiting Integrin adhesion
Hemostasis: Platelet degranulation
Muscle contraction: Smooth Muscle Contraction
Gene Ontology:
Molecular function: cadherin binding; integrin binding; LIM domain binding; protein binding; vinculin binding; actin binding; actin filament binding; phosphatidylinositol binding; phosphatidylserine binding; structural constituent of cytoskeleton
Biological process: platelet aggregation; actin cytoskeleton organization; cell-cell adhesion; cell-cell junction assembly; regulation of focal adhesion assembly; cell adhesion; cortical microtubule organization; integrin activation; integrin-mediated signaling pathway
Cellular component: adherens junction; centriolar satellite; cytosol; extracellular exosome; focal adhesion; plasma membrane; cell surface; cytoplasm; extracellular region; ruffle; cytoskeleton; ruffle membrane
Genetic constraint (gnomAD): Loss-of-function variants: 56 observed, 295.83 expected, observed/expected ratio (o/e) 0.19, 90% interval 0.15 to 0.24. The upper end of that interval is the gene's LOEUF score, 0.24, which puts it in group 1 of 6, group 1 being the genes least tolerant of losing a copy. Missense variants: 2,433 observed, 3,345.2 expected, observed/expected ratio (o/e) 0.73, 90% interval 0.7 to 0.75. Synonymous variants: 1,119 observed, 1,302.4 expected, observed/expected ratio (o/e) 0.86, 90% interval 0.82 to 0.9.
Homologues: Orthologues: chimpanzee TLN1 (99% identical), macaque TLN1 (99% identical), dog TLN1 (99% identical), rabbit TLN1 (99% identical), mouse Tln1 (99% identical), rat Tln1 (99% identical), pig TLN1 (98% identical), guinea pig TLN1 (97% identical), tropical clawed frog tln1 (86% identical), zebrafish tln1 (83% identical), Drosophila melanogaster rhea (48% identical), Caenorhabditis elegans tln-1 (38% identical). Paralogues in human: TLN2 (76% identical), TLNRD1 (5% identical).
Diseases named in the same sentence as TLN1 in open-access papers:
TLN1 is named in the same sentence as 148 diseases in open-access papers, as found by Europe PMC text mining. Sharing a sentence is not in itself a finding about the gene and the disease. The quoted sentences say what the papers report.
prostate carcinoma (28 papers, 2012 to 2026). A carcinoma that arises from epithelial cells of the prostate gland. "Previous investigations indicated dysregulation of Talin-1 is associated with patients’ survival outcomes in colorectal and prostate cancers and oral SCC and nasopharyngeal carcinoma." (PMID 37013489, 2023). "Per our results, in the literature, the association of Talin-1 upregulation with invasive cancer phenotype and higher stages of gastric and prostate cancer as well as nasopharyngeal carcinoma and oral SCC has been reported." (PMID 37013489, 2023). "Loss of talin-1 results in reduced in vivo metastasis of prostate cancer cells via the FAK-Src complex and AKT kinase signaling." (PMID 36698399, 2022). "Loss of talin-1 leads to diminished in vivo metastasis of prostate cancer cells via FAK–Src complexes and AKT kinase signalling." (PMID 33431906, 2021). "The miR-124 as a putative tumor suppressor was down-regulated in prostate cancer and caused overexpression of talin-1 in prostate cancer." (PMID 31700834, 2019). "Previous studies have shown that overexpression of talin-1 is associated with increased invasion and reduced survival in oral squamous cell carcinoma, as well as migration, invasion, and apoptosis resistance in prostate cancer cells." (PMID 36698399, 2022). "TLN1 has been associated with enhanced cellular migration and integrin activation in cancers such as AML and prostate cancer." (PMID 41224720, 2025). "The expression level of Talin-1 is reduced in endometrial cancer tissue, and Talin-1 promotes prostate cancer metastasis." (PMID 41203126, 2025). "Multiple studies have reported that overexpression of talin-1 can promote prostate cancer cell adhesion, migration, and invasion." (PMID 39189262, 2024). "Integrin-linked kinase (ILK), plectin (PLEC), paxillin (PXN), talin 1 (TLN1), and vinculin (VCL) are other adhesome proteins that were implicated in prostate cancer and that showed biomarker potential in this cancer type." (PMID 38255186, 2023). "High expression levels of Talin-1 correlated with invasion and lower survival rates in prostate cancer, colon cancer, nasopharyngeal carcinoma, and oral SCC." (PMID 37013489, 2023). "Accumulating evidence suggests that the expression of Talin-1 is dysregulated in various malignant neoplasms, such as colorectal cancer, hepatocellular carcinoma, prostate cancer, and oral squamous cell carcinoma." (PMID 33750407, 2021). "Talin-1 overexpression markedly enhanced the migration and invasion potential of human prostate cancer cells by activating ECM–integrin-mediated signaling and promoting anoikis resistance." (PMID 33750407, 2021). "A recent study showed that Talin-1 played an important role in integrin activation, cell adhesion, migration, invasion, and anoikis of prostate cancer cells, and promotion of prostate cancer bone metastasis." (PMID 33750407, 2021). "We selected 4 candidate autoantibodies against 4 proteins (TARDBP, PARK7, Talin 1, TLN1, and CALD1) that have been previously shown to be associated with prostate cancer." (PMID 31404106, 2019). "In addition, Talin-1 can promote cancer cell adhesion, migration and invasion, and may represent a diagnostic marker of aggressive phenotypes and a potential therapeutic target for prostate cancer and OSCC." (PMID 25925041, 2015). "Subsequently, miR-124 and talin 1 were examined and compared in a panel of prostate cancer cell lines and a normal prostate epithelial cell line, which showed similar results to the tissue specimens (p < 0.05)." (PMID 25969668, 2015). "By down-regulation of talin 1, miR-124 impairs the adhesion, migration, and invasion of prostate cancer cells." (PMID 25969668, 2015). "Previous studies demonstrated that the expression of Talin-1 was highly associated with endometrioid carcinoma, oral squamous cell carcinoma (OSCC), prostate cancer and hepatocellular carcinoma." (PMID 25925041, 2015).
prostate carcinoma (continued). "Considering the varying levels of talin 1 among the prostate cancer cell lines, Du145 cells were selected for evaluation." (PMID 25969668, 2015). "Similar to talin 1 knockdown, we found impaired adhesion of prostate cancer cells by over-expression of miR-124." (PMID 25969668, 2015). "Recently, Sakamoto and colleagues found that overexpression of Talin-1 enhanced prostate cancer cell adhesion, migration and invasion by stimulating FAK, Src and GSK3β independently of integrin signaling and also conferred resistance to anoikis." (PMID 25925041, 2015). "MiR-124 was down-regulated in prostate cancer specimens and cell lines, while talin 1 was over-expressed in prostate cancer specimens and cell lines." (PMID 25969668, 2015). "We searched for potential miRNAs related to talin 1 using an online bioinformatics tool, and screened miRNAs by luciferase reporter assays in prostate cancer cells." (PMID 25969668, 2015). "Evidently, miR-124 targeted talin 1 directly, resulting in suppression of adhesion and motility in prostate cancer cells." (PMID 25969668, 2015). "An abnormal increase in the expression level of talin 1 has been recently reported in prostate cancer." (PMID 25969668, 2015). "We recently demonstrated a significant correlation between talin-1 overexpression and metastasis in a mouse model of prostate tumorigenesis and in human prostate cancer progression." (PMID 24497940, 2014). "Loss of expression of the intracellular focal adhesion signaling effectors talin-1 and integrin linked kinase (ILK) sensitized human prostate cancer to anoikis." (PMID 24497940, 2014). "Talin-1 functionally contributes to anoikis-resistance and prostate cancer metastasis by enhancing focal adhesion formation and Akt-survival signaling." (PMID 24497940, 2014). "Previous research had indicated that Tln1 overexpression could promote prostate cancer cell metastasis and invasion through focal adhesion signaling and anoikis resistance, which may be related to AKT signaling activation." (PMID 40819162, 2025). "Furthermore, Talin-1 knockdown in prostate cancer and colorectal cancer cell lines has been shown to reduce their migration and proliferation." (PMID 37013489, 2023). "TLN1 is located in focal adhesion (FA), which regulates integrin signalling and promotes metastasis in different cancers, including prostate cancer, colon cancer, and oral squamous cell carcinoma." (PMID 35285795, 2022). "TLN1 played an essential role in integrin activation, which was correlated with a metastatic phenotype of malignant tumors, such as breast cancer, hepatocellular carcinoma, and prostate cancer." (PMID 35612641, 2022). "Likewise, miR-124 was effective at targeting TLN1 and interfering with dynamic activity of prostate cancer cells." (PMID 34732818, 2021). "The study showed that the overexpression of TLN1 in cells such as prostate cancer cells could lead to increased signaling of AKT and FAK pathways." (PMID 31269666, 2019). "We confirmed that talin 1 is a direct and functional target of miR-124 in prostate cancer." (PMID 25969668, 2015). "By directly targeting talin 1, an integrin-associated cytoskeletal protein in focal adhesion formation, miR-124 suppresses the adhesion and motility of prostate cancer cells and down-regulates the focal adhesion kinase (FAK)/Akt pathway, suggesting the involvement of talin 1 in prostate cancer." (PMID 25969668, 2015). "Upregulation of Talin-1 expression is documented in gastric cancer, mucosal SCC, and prostate cancers; conversely, its downregulation is shown in colorectal cancer and hepatocellular carcinoma." (PMID 37013489, 2023). "TLN1 S425 is phosphorylated by cyclin-dependent kinase 5 (CDK5), which controls the metastatic potential in prostate cancer." (PMID 31108958, 2019). "The anoikis-inducing effect of the lead quanazoline compound DZ-50 was investigated in human prostate cancer cell lines variably expressing the FAC proteins, talin-1 and ILK." (PMID 24497940, 2014).
prostate carcinoma (continued). "In the non-type molecular subtype, TLN1 is significantly hyperphosphorylated at S425 in the head domain (band 4.1, ezrin, radixin, moesin homology domain), a site also known to be hyperphosphorylated in prostate cancer." (PMID 31108958, 2019).
breast carcinoma (17 papers, 2014 to 2026). "In breast cancer, knockdown of talin-1 and blockade of its binding with integrin interfered with the formation of FA and the FAK-AKT signaling pathway." (PMID 40362467, 2025). "Several studies have shown that TLN1 promotes tumor development and drug resistance in breast cancer." (PMID 38731868, 2024). "Specifically, TLN1 expression in TNBC cells is much higher than in other subtypes of breast cancer cell lines, and silencing TLN1 significantly attenuated the malignancy of MDA-MB-231 cells, reducing TNBC tumour growth and lung metastasis." (PMID 35285795, 2022). "For instance, reduced expression of talin-1 enhanced chemosensitivity of breast cancer cells to docetaxel drug, which proposes talin-1 as a potential therapeutic target." (PMID 31269666, 2019). "Moreover, in PAM50 breast cancer molecular subtypes, we found TLN1 exon 17b inclusion to be lowest in normal-like and highest in basal-like tumors." (PMID 36880935, 2023). "Correlation between TLN1 and the integrin family in different types of the TCGA-BRCA dataset from TIMER database showed that TLN1 may play an important role in breast cancer, especially in TNBC." (PMID 35285795, 2022). "Moreover, a previous study found higher TLN1 transcripts in TNBC than in other clinical breast cancer subtypes." (PMID 35285795, 2022). "Furthermore, there are notable similarities between this network and that present in human basal and claudin-low breast cancer cell lines, including increased tyrosine phosphorylation of Met, Cav1, Bcar1 and Tln1." (PMID 25200860, 2014). "Talin-1 (TLN1), a cytoplasmic adapter protein, mediates cell–cell adhesion by interacting with integrin β1 in breast cancer cells." (PMID 37681860, 2023). "Considering that TLN2 shares 76% protein sequence identity with TLN1, we analysed the expression of TLN2 in the breast cancer dataset from TCGA database." (PMID 35285795, 2022). "High levels of both TLN1 and CFL1 are reported in the secretome of breast cancer cell lines (including, metastatic, triple-negative, MCF7 ER-positive, and triple-negative), confirming their release into the ECM." (PMID 33267867, 2020). "Talin 1 (TLN1) is a cytoskeletal protein that functions in extravasation and breast cancer cell migration." (PMID 33267867, 2020). "Model 2 included four candidate predictors specific for breast cancer in this study: Ras-related protein Rap-1A (RAP1A, LVVLGSGGVGK), Integrin alpha-IIb (ITGA2B, VYLFLQPR), FLNA (ANLPQSFQVDTSK), and Talin-1 (TLN1, LAQAAQSSVATITR)." (PMID 33267867, 2020). "In the current study, we successfully targeted dysregulated CTNNA1, CTNNB1, TLN1, VCL, PXN, and ACTN1 genes by delivering respective siRNAs with the help of nano-sized CA particles in breast cancer cells as well as in a murine breast cancer model." (PMID 31269666, 2019). "They concluded that TLN1 is a regulator of response to docetaxel and a potential therapeutic target for TNBC, but not in other types of breast cancer." (PMID 35285795, 2022). "Moreover, our finding that TLN1 exon 17b is present in some cancer cell lines but absent in others suggests that TLN1 alternative splicing might alter cancer cell behavior, and whose level might be useful for stratification of certain molecular subtypes of breast cancer." (PMID 36880935, 2023).
hepatocellular carcinoma (16 papers, 2015 to 2023). A malignant tumor that arises from hepatocytes. "FLNA is associated with cell proliferation and invasion in hepatocellular carcinoma, while TLN1 participates in the invasion of ovarian serous carcinoma and is active in hepatocellular carcinoma cells." (PMID 30984788, 2019). "In cell models of hepatocellular carcinoma, talin-1 inhibition or knockdown led to decreased proliferation, decreased migration, and enhanced anoikin effects, which suggests that the reverse of the EMT process is taking place." (PMID 34684727, 2021). "In contrast, high TLN1 expression along with low microRNA-330-5p expression was reported in hepatocellular cancer tissues." (PMID 32566035, 2020). "Five genes with de novo damaging alleles PIK3CA, TLN1 CYLD, and MAP2K1, are linked with cholangio- and hepatocellular carcinomas in addition to congenital syndromes and conditions related to tissue overgrowth." (PMID 27955658, 2016). "In hepatoma-derived HepG2 cells in which TLN1 was knocked down, HBV replicated efficiently and independent of HBx expression." (PMID 27775586, 2016). "Besides this, TLN1 overexpression promoted hepatocellular carcinoma epithelial-mesenchymal transition and induced metastasis." (PMID 35069901, 2022). "Talin-1 can also significantly promote hepatocellular carcinoma cell proliferation and metastasis." (PMID 33750407, 2021). "Six genes carrying DNVs were associated with human developmental disorders involving epithelial, connective or bone morphologies (PXDN, RTEL1, ANKRD11, MAP2K1, CYLD, ACAN) and four linked with cholangio- and hepatocellular carcinomas (PIK3CA, TLN1 CYLD, MAP2K1)." (PMID 27955658, 2016). "It was shown to be downregulated and might function as a tumor suppressor by targeting Myc, FSCN1 in gastric cancer, ZEB1 in oral squamous cell carcinoma, CRKL in hepatocellular carcinoma, TLN1 in nasopharyngeal carcinoma, AKT1 in melanoma, or BCL2 and SP1 in esophageal carcinomas." (PMID 33414893, 2020). "For example, in hepatocellular carcinoma, LINC00488 acts as a ceRNA, which could competitively sponge miR-330-5p to regulate TLN1, thus affecting the cell growth and angiogenesis in HCC." (PMID 33600548, 2021). "Talin-1 (TLN-1) and TLN-2 are implicated in many cellular processes, but their roles in hepatocellular carcinoma (HCC) remain unclear." (PMID 26822056, 2016). "However, Talin-1 expression in hepatocellular carcinoma (HCC) was controversial." (PMID 25925041, 2015). "Moreover, the downregulation or the absence of talin-1 was found in hepatocellular carcinoma (HCC), endometriosis, and endometrioid carcinomas." (PMID 37942198, 2023).
colorectal cancer (10 papers, 2020 to 2025). A primary or metastatic malignant neoplasm that affects the colon or rectum. "Given that TALIN-1, MRE11, and CCT8 interact with E-cadherin, that FASN, FLNA, and DDX3X are implicated in EMT, and that FKBP4 expression is upregulated in colon cancers, we examined E-cadherin expression in human colorectal carcinoma HCT116 cells under the FKBP4 knockdown." (PMID 41203126, 2025). "A recent study performed by our group using talin-1 demonstrated that low expression of talin-1 on both mRNA and protein levels was significantly associated with advanced pathological features and worse disease-specific survival (DSS) in patients with colorectal cancer (CRC)." (PMID 37942198, 2023).
oral squamous cell carcinoma (8 papers, 2015 to 2024). "TLN1 is overexpressed in several tumors, such as prostate, liver, and oral squamous cell carcinomas." (PMID 38731868, 2024). "Recent studies have shown that the overexpression of TLN1 in oral squamous cell carcinoma, liver cancer, and prostate cancer is related to tumor invasion, metastasis, or poor differentiation." (PMID 36175877, 2022). "TLN1 overexpression is also correlated with advanced and aggressive oral squamous cell carcinoma." (PMID 31108958, 2019). "For example, TLN1, a cytoskeletal protein that was upregulated in LKB1-attenuated ICCs is directly correlated with invasion and metastasis of human oral squamous cell carcinoma." (PMID 26056085, 2015).